BDNF (brain derived neurotrophic factor)
Diseases named in the same sentence as BDNF in open-access papers (continued):
Sharing a sentence is not in itself a finding about the gene and the disease.
complication (2 papers, 2020 to 2023). Any disease or disorder that occurs during the course of, or because of, another disease, treatment, or procedure. "Several studies have additionally suggested that lower BDNF levels may be a risk factor of diabetic neurovascular complications." (PMID 36970903, 2023). "Several studies also suggest that lower BDNF levels may be a risk factor of diabetic neurovascular complications." (PMID 36970903, 2023).
delirium tremens (2 papers, 2017 to 2023). "In keeping with this assertion, lower levels of BDNF are associated with delirium tremens." (PMID 28280733, 2017). "It has been reported that BDNF is associated with the pathogenesis of several neuropsychiatric disorders such as schizophrenia, depression, Alzheimer's disease, Huntington's chorea, and alcohol withdrawal delirium." (PMID 28280733, 2017). "However a direct comparison cannot apply as these two conditions have phenomenological and aetiological differences; BDNF levels are increased in vitro and in vivo following acute alcohol exposure but are reduced with chronic use and genetic variants are associated with alcohol withdrawal delirium." (PMID 28280733, 2017).
Delusion (2 papers, 2013 to 2023). A delusion is a fixed false belief held despite evidence to the contrary. "The mechanism may be related with increased brain-derived neurotrophic factor (BDNF) levels and 5-hydroxytryptamine (5-HT) release in the brain, and low-frequency rTMS also are equally effective for symptoms such as auditory hallucination and delusions." (PMID 37221495, 2023).
developmental disabilities (2 papers, 2018 to 2020). "Accordingly, future studies should investigate the relationship between BDNF and metabolic outcomes following programmed exercise interventions in children with developmental disabilities." (PMID 30363954, 2018).
Dravet syndrome (2 papers, 2021 to 2023). "AntagoNATs effectively increased the expression of brain-derived neurotrophic factor (BDNF), a protein important in memory development, and the healthy allele of SCN1A, the haploinsufficiency of which triggers Dravet syndrome." (PMID 34899268, 2021).
dyslipidaemia (2 papers, 2018 to 2020). "Plasma BDNF levels and a functional BDNF Val66Met (rs6265) polymorphism were reported to be associated with PTSD, as well as with increased body mass index (BMI) and dyslipidaemia in healthy subjects and patients with cardio-metabolic diseases, but these results are controversial." (PMID 30542302, 2018).
embryonic carcinoma (2 papers, 2016 to 2021). "Furthermore, it was demonstrated that marked dephosphorylation of tau protein occurred after BDNF application in differentiated P19 mouse embryonic carcinoma cells through the phosphatidylinositol-3 kinase (PI3K)/Akt signaling pathways." (PMID 34071978, 2021). "BDNF treatment also dephosphorylated tau protein at S202, T205, AT180, and S262 sites in neuronally differentiated P19 mouse embryonic carcinoma cells through the PI3K/Akt signaling pathway." (PMID 34071978, 2021).
emphysema (2 papers, 2012 to 2025). "Thus, it might be speculated that the disappearance of the association between BDNF and FEV1 in spirometric GOLD stage 4 was due to a strong influence of emphysema on the FEV1 reduction in this subgroup." (PMID 23245944, 2012). "Brain-Derived Neurotrophic Factor (BDNF) significantly contributes to fibrosis and emphysema in COPD." (PMID 41226620, 2025). "Brain-derived Neurotrophic Factor (BDNF) is a key regulator of neuronal plasticity, whereas Transforming Growth Factor-β1 (TGF-β1) plays a crucial role in tissue repair and emphysema pathogenesis." (PMID 23245944, 2012).
end-stage renal disease (2 papers, 2023 to 2025). "For instance, patients with end-stage renal disease demonstrated a significant increase in serum BDNF levels 2 years after renal transplantation, indirectly supporting a positive correlation between renal function and systemic BDNF status." (PMID 40791659, 2025).
enuresis (2 papers, 2023 to 2026). An elimination disorder characterized by urinary incontinence, whether involuntary or intentional, which is not due to a medical condition and which occurs at or beyond an age at which continence is expected (usually 5 years). "Studies examining BDNF in enuresis often involve urinary BDNF, which reflects local bladder production rather than central BDNF activity." (PMID 42041783, 2026). "Further research is needed to clarify the specific roles of BDNF in the development and manifestation of these conditions and to fully elucidate the complex relationship between BDNF, ADHD, and enuresis." (PMID 42041783, 2026).
fetal macrosomia (2 papers, 2018 to 2023). "This tendency also applies to the fetal macrosomia group, which similarly demonstrates elevated amniotic BDNF levels." (PMID 30622436, 2018).
fluorosis (2 papers, 2023 to 2025). "We demonstrated that ASP could regulate the brain damage caused by fluorosis through the SIRT1/BDNF/TrkB signaling pathway, and reported the possible part played by ASP in preventing and treating fluorosis." (PMID 39041630, 2025). "We analyzed the effect of ASP on the BDNF/TrkB pathway in brain tissue in rats suffering from fluorosis." (PMID 39041630, 2025).
food allergy (2 papers, 2021 to 2025). Gastrointestinal disturbances, skin eruptions, or shock due to allergic reactions to allergens in food. "Our results, show that DNAm levels of BDNF are significantly decreased in PA compared with NA participants, suggesting that epigenetic modification of the BDNF gene is associated with food allergy." (PMID 33571165, 2021).
fracture (2 papers, 2015 to 2022). "Here we examined functional polymorphisms from BDNF and serotonin-related genes as predictors of depressive symptoms after hip fracture." (PMID 25781924, 2015). "Analyses also indicated BDNF Met/Met carriers were more likely to have poorer functional recovery scores for a year after hip fracture as a result of BDNF genotype on depressive symptoms." (PMID 25781924, 2015).
gastric tumors (2 papers, 2016 to 2021). "BDNF expression was also increased in gastric tumors from stage III patients in comparison with those from other-stage patients (P <0.001)." (PMID 27458153, 2016). "Moreover, gastric tumors with metastases showed increased expression levels of both TrkB and BDNF when compared to those without metastases (P <0.001)." (PMID 27458153, 2016).
gastrointestinal infection (2 papers, 2011 to 2017). "BDNF can improve patients' spiritual well-being and autoimmunity, and can increase the antidepressant properties, reducing the rate of gastrointestinal infection." (PMID 29230173, 2017). "Phenolics from blueberry reduced gastrointestinal infection of patients with CVT by improving antidepressant activity via upregulation of miR-155-mediated BDNF." (PMID 29230173, 2017). "BDNF plays an important role in the development of the enteric nervous system, defense against intestinal infection, and the modulation of gastrointestinal motility." (PMID 21738758, 2011). "Therefore, blueberry inhibits gastrointestinal infection by improving autoimmune activity of CVT patients via miR-155-mediated regulation of BDNF level." (PMID 29230173, 2017). "We hypothesized that blueberry extracts can decrease depressive symptoms by regulating BDNF, and reducing gastrointestinal infection." (PMID 29230173, 2017).
generalized tonic-clonic seizure (2 papers, 2018 to 2021). "They found a significant decrease in serum BDNF levels in patients after generalized tonic clonic seizures, at 1 and 72 h after seizures in this group." (PMID 34899313, 2021). "In our study, reduced serum levels of BDNF correlated with age, adrenergic and sudomotor functions, the total autonomic score (mCASS), and cerebral autoregulation (ASI), particularly in patients with focal to bilateral tonic-clonic seizures." (PMID 30524358, 2018).
gestational diabetes (2 papers, 2022 to 2023). Carbohydrate intolerance first diagnosed during pregnancy. "The Objective of our study was to investigate the influence of dietary (dGDM) and insulin-dependent (iGDM) gestational diabetes (GDM) on BDNF blood levels of corresponding maternal-neonatal pairs and compare them to pregnancies unaffected by GDM." (PMID 35736415, 2022).
glucocorticoid resistance (2 papers, 2019 to 2025). "Glucocorticoid resistance poses a risk factor for AD, and GR phosphorylation through brain-derived neurotrophic factor (BDNF) signaling is involved in remodeling synaptic structure and plasticity." (PMID 40362450, 2025). "In models of glucocorticoid resistance, DUSP1 downregulation can be explained by the deactivation of BDNF signaling, taking into account that DUSP1 is a transcriptional target of BDNF and glucocorticoids." (PMID 31018603, 2019).
Granuloma (2 papers, 2010 to 2025). A compact, organized collection of mature mononuclear phagocytes, which may be but is not necessarily accompanied by accessory features such as necrosis. "Sarcoid granulomas in the mediastinal lymph node also showed positive immunoreactivity for NGF, BDNF, NT-3, TrkA, TrkB and TrkC, localized to the granulomas and the surrounding lymphoid tissue." (PMID 21059230, 2010). "No or less immunoreactivity for NGF, BDNF or NT-3 was found within fibrotic tissue around granulomas." (PMID 21059230, 2010).
head and neck cancer (2 papers, 2017 to 2024). A primary or metastatic malignant neoplasm affecting the head and neck. "To definitively demonstrate that CAF-derived BDNF impacted tumor growth and lymphatic metastasis, we selectively down-modulated BDNF expression in the CAF compartment in an animal model of head and neck cancer." (PMID 28966935, 2017).
hearing disorder (2 papers, 2019 to 2024). A disorder characterized by the partial or complete loss of the ability to detect sounds due to damage to the ear structures or inability of the brain to properly interpret or process the auditory signals it receives from the anatomic structures of the ear. "The known safety of BDNF and NT-3 from human studies, combined with the potential for effective local delivery to the inner ear, presents an attractive approach that should be evaluated clinically in hearing disorders, such as hidden hearing loss, where a neurotrophic mechanism may be beneficial." (PMID 31671109, 2019).
hematoma (2 papers, 2022). A hematoma is a collection of blood from a vascular structure into an extravascular space. "Then, the amount of BDNF in the cerebral tissues around the hematoma cavity was measured to elucidate the mode of action of rCellSaic." (PMID 35966129, 2022). "In conclusion, HBO improves consciousness, cognitive function, and prognosis in patients with severe or moderate TBI through decreasing TBI-induced hematoma volumes, promoting the recovery of EEG rhythms, and modulating the expression of serum NSE, S100β, GFAP, BDNF, NGF, and VEGF." (PMID 36034283, 2022). "HBO may be an effective treatment for patients with TBI to improve consciousness, cognitive function and prognosis through decreasing TBI-induced hematoma volumes, promoting the recovery of EEG rhythm, and modulating the expression of serum NSE, S100β, GFAP, BDNF, NGF, and VEGF." (PMID 36034283, 2022).
Hepatitis (2 papers, 2022 to 2025). Inflammation of the liver. "As mentioned, in previous studies of bee venom in cell models which seem to lack the significance of BDNF/TrkB/CREB, such as studies on steatohepatitis, wound healing, and hepatitis, bee venom also showed a remarkable ability to upregulate the Nrf2/HO-1 pathway." (PMID 35163115, 2022).
Hydrocephalus (2 papers, 2020 to 2026). Hydrocephalus is an active distension of the ventricular system of the brain resulting from inadequate passage of CSF from its point of production within the cerebral ventricles to its point of absorption into the systemic circulation. "Third, we did not correlate BDNF levels with neuroimaging data; it is likely that BDNF levels can be affected by acute and chronic structural changes of the brain, such as loss of tissue, atrophy, or hydrocephalus." (PMID 32565776, 2020).
hypercoagulability (2 papers, 2021 to 2024). "We hypothesized that BDNF levels (measured at baseline only) would show an inverse association with hemostatic factors of a hypercoagulable state at baseline and in response to stress, adjusting for important demographic and health characteristics known to affect hemostasis." (PMID 33504912, 2021).
hyperthyroidism (2 papers, 2022 to 2024). Overactivity of the thyroid gland resulting in overproduction of thyroid hormone and increased metabolic rate. "According to the research, factors that can induce mania also increase BDNF, e.g., administration of amphetamines, hyperthyroidism or antidepressants." (PMID 36294388, 2022). "Moreover, hyperthyroidism has been found to potentially result in a decline in brain-derived neurotrophic factor (BDNF) levels." (PMID 38419953, 2024).
IgA nephropathy (2 papers, 2022 to 2023). "In line with our findings, the intronic variants of BDNF were reported to be associated with disease severity presenting as proteinuria in patients with IgA nephropathy." (PMID 36782254, 2023).
imbalance (2 papers, 2020 to 2025). "Proposed mechanisms include immune dysfunction, neuroendocrine imbalance, microinflammation, brain-derived neurotrophic factor (BDNF) depletion, gut-brain-skin axis dysregulation, and medication-induced disruptions in hair cycling." (PMID 40557018, 2025).
inflammatory skin disease (2 papers, 2013 to 2022). Inflammatory skin disorders covers a broad category that includes many conditions ranging in severity, from mild itching to grave medical health complications These disorders are common in people of all ages and races. "In addition, BDNF has been shown to inhibit eosinophil apoptosis and modulate eosinophil function, suggesting BDNF involvement in the pathophysiology of pruritic inflammatory skin diseases such as AD." (PMID 36362520, 2022). "There are various neuropeptides involved in inflammatory skin disorders, which include substance P (SP), calcitonin gene-related peptide (CGRP), brain-derived neurotrophic factor (BDNF), corticotropin-releasing factor (CRF) and interleukin 31 (IL-31)." (PMID 23108364, 2013).
inner ear disease (2 papers, 2018 to 2021). "The therapeutic potential of factor combinations such as BDNF and C3 are of great importance for the development of drugs for the treatment of inner ear diseases." (PMID 33776650, 2021). "Thus, NPSNPs carrying BDNF are suitable for the treatment of inner ear disease and for the protection and the support of SGNs." (PMID 29584754, 2018).
interstitial lung disease (2 papers, 2014 to 2024). A diverse group of lung diseases that affect the lung parenchyma. "However, in a study on eight individuals affected by respiratory bronchiolitis-associated interstitial lung disease, no changes in BDNF were revealed, but a faint expression of neurotrophin-3 and other neurotrophin receptors was detected." (PMID 39403060, 2024).
kidney failure (2 papers, 2022 to 2023). An acute or chronic condition that is characterized by the inability of the kidneys to adequately filter the blood. "This study compares the levels of neuron specific enolase (NSE), brain-derived neurotrophic factor (BDNF), neurofilament light chain (NfL), and circulating plasma extracellular vesicles (EVs) in kidney-failure patients before KT and at a two-year follow up." (PMID 37047601, 2023).
leiomyoma (2 papers, 2012 to 2022). A well-circumscribed benign smooth muscle neoplasm characterized by the presence of spindle cells with cigar-shaped nuclei, interlacing fascicles, and a whorled pattern. "We performed a clustering analysis of a leiomyoma gene set with the addition of BDNF for MyoF and F samples in both race groups." (PMID 36066972, 2022). "The levels of TrkB and BDNF transcripts were significantly increased in uterine leiomyosarcoma as compared to those in myometrium and leiomyoma, whereas NT4/5 expression was insignificant among the tissues." (PMID 22911740, 2012). "In uterine leiomyosarcoma samples obtained from patients, the levels of BDNF and TrkB were significantly high as compared with uterine myometrium and leiomyoma." (PMID 22911740, 2012). "We also demonstrated that the levels of TrkB and BDNF transcripts were elevated in samples obtained from patients with leiomyosarcoma as compared with those of uterine myometrium and leiomyoma." (PMID 22911740, 2012).
liver cirrhosis (2 papers, 2021). "Brain-derived neurotrophic factor (BDNF) was recently used as a marker for the nutritional status in children and adolescents with liver cirrhosis due to biliary atresia." (PMID 34062967, 2021). "BDNF level is significantly lower in patients with liver cirrhosis induced by hepatitis B virus (HBV)." (PMID 34684653, 2021).
lung squamous cell carcinoma (2 papers, 2016 to 2024). "However, it has been reported that BDNF had a high expression level in lung squamous cell carcinoma and NSCLC, linked to tumor proliferation and invasion." (PMID 39036344, 2024). "The purpose of this study was to explore the function of BDNF in lung squamous cell carcinoma (SCC) and adenocarcinoma (ADC)." (PMID 26926340, 2016).
lymphoma (2 papers, 2017 to 2024). A malignant (clonal) proliferation of B- lymphocytes or T- lymphocytes which involves the lymph nodes, bone marrow and/or extranodal sites. "In conclusion, our study provides valuable insights into the potential association between IL-4, BDNF, neopterin, and depressive symptoms in lymphoma patients undergoing R-CHOP chemotherapy." (PMID 39355088, 2024). "This study aims to address this gap by investigating the association between IL-4, BDNF, neopterin and depressive symptoms in lymphoma patients." (PMID 39355088, 2024). "The purpose of the study was to investigate the association between levels of IL-4, BDNF, neopterin, and depressive symptoms in lymphoma patients receiving consecutive cycles of chemotherapy." (PMID 39355088, 2024). "The effect of different cycles of R-CHOP on IL-4, BDNF and neopterin levels of all lymphoma patients (n = 70)." (PMID 39355088, 2024). "ALC or KET treatment for 24 h significantly down-regulated the expression of p-CREB, p-Akt, B cell lymphoma/lewkmia-2 (Bcl-2), BDNF and PKA." (PMID 28874724, 2017).
mastitis (2 papers, 2021 to 2023). Inflammation of breast tissue during lactation or postpartum due to an obstructed duct or infection. "The impact of previous COVID-19 infection and mastitis on the concentration of BDNF and NGF in human milk was investigated." (PMID 33917718, 2021). "Whether the reduced BDNF levels in milk from mothers with mastitis influences neonatal development remains investigated." (PMID 33917718, 2021). "BDNF concentration in human milk was lower in mothers with mastitis than in mothers without mastitis." (PMID 33917718, 2021). "BDNF was lower in mothers with mastitis than in mothers without mastitis." (PMID 33917718, 2021). "BDNF and NGF concentrations were comparable in milk from mothers with or without mastitis." (PMID 33917718, 2021).
mastocytosis (2 papers, 2017 to 2025). A clonal myeloproliferative neoplasm characterized by the proliferation and accumulation of neoplastic mast cells in one or multiple organs or organ systems. "Since NTs can be released by mast cells as well as bone marrow stromal cells, our data, together with our recent report demonstrating SM induction by BDNF-mediated activation of TRKB, suggest an important role of autocrine and/or paracrine activation of TRKs in the pathogenesis of mastocytosis." (PMID 29088753, 2017).